MYD88 (MYD88 innate immune signal transduction adaptor)
Diseases named in the same sentence as MYD88 in open-access papers (continued):
Sharing a sentence is not in itself a finding about the gene and the disease.
influenza (25 papers, 2009 to 2024). An acute viral infection of the respiratory tract, occurring in isolated cases, in epidemics, or in pandemics; it is caused by serologically different strains of viruses (influenzaviruses) designated A, B, and C, has a 3-day incubation period, and usually lasts for 3 to 10 days. "IRAK4 kinase-dead knock-in (IRAK4KDKI) mice, which have a catalytically inactive form of IRAK4 that precludes MyD88-dependent signaling, were shown to be susceptible to influenza with a slight delay in the meantime to death compared to wildtype mice." (PMID 34282358, 2021). "While the TLR4/TRIF signaling axis was suggested to be central for ALI, MyD88 has also been implicated in the host response to influenza." (PMID 34282358, 2021). "MyD88 signaling was found to be important for protecting mice during primary influenza infection, as MyD88−/− knockout mice were more susceptible." (PMID 32477965, 2020). "Additionally, MyD88 deficiency resulted in significantly higher lung pathology and diminished the cytokine response to influenza after infection when compared to wildtype mice or TRIF-/- mice." (PMID 34282358, 2021). "OVA and influenza vaccination studies found MyD88 played an important role in AddaVax and AddaS03 adjuvant effects." (PMID 38793782, 2024). "The role of IRAK4, the first enzyme recruited to MyD88 for signaling, was also examined during influenza infection." (PMID 34282358, 2021). "As MyD88 plays a role in immune system derived damage during influenza infection in mammals, it would be interesting to know if chMyD88 activation is significantly different from the duck." (PMID 32477965, 2020). "Studies have shown that TCMs can play a role in the treatment of influenza by TLR7 mediated MyD88-dependent signaling pathway." (PMID 30151032, 2018). "In accordance, mice deficient for TLR3 and TLR7 (tlr3/tlr7−/−) or the common TLR adapter MyD88 (myd88−/−) demonstrated an increased lethality upon infection with influenza." (PMID 23483993, 2013). "Although IPS-1 is involved in IFN-I expression, deletion of IPS-1 can be compensated by MyD88 signaling after influenza infection." (PMID 21383977, 2011). "TLR7 expression on pDCs plays a cell-specific role against influenza through MyD88-dependent IFN-α induction." (PMID 21108806, 2010). "Heer and coworkers found that, in Myd88 knockout mice, antibodies specific for influenza exhibited defective class switching." (PMID 19214214, 2009). "To investigate the possibility that HB36.6 may induce other host responses that could contribute to protection, we tested HB36.6 for protection against influenza in two severe immune-deficient mouse models: NOD SCID gamma (SCID) and MyD88-/- mice." (PMID 26845438, 2016). "TLR7 dependent MyD88 activation has been reported to accelerate clearance of influenza in mice." (PMID 23483993, 2013). "While MyD88-/- mice were found to be more susceptible to primary influenza infection than wildtype control mice, they were protected from a secondary influenza challenge after a low dose primary infection suggesting that MyD88 was not required for protection against a secondary influenza infection." (PMID 34282358, 2021). "Huoxiang Suling Shuanghua Decoction exerts an anti-influenza effect by affecting the expressions of mRNA and protein including TLR4, CD14, MyD88, NF-kB p65, HIF-1α, VEGF, IL17A, IL6, and inhibiting the accumulation of inflammation." (PMID 36386710, 2022). "Next, eight key targets were identified, including TLR4, CD14, MyD88, NF-κB p65, HIF1 α, VEGF, IL17A, and IL6, which were verified to be key targets for HSSD in the treatment of influenza." (PMID 36386710, 2022). "Moreover, MyD88 and MyD88-mediated signaling pathways are also important for the induction of primary and boost immune responses; in fact, MyD88−/− mice showed a lower production of IgG2a/c and lower numbers of recall memory B cells versus the littermate controls in the context of influenza vaccine." (PMID 33530627, 2021).
influenza (continued). "A549 cells infected with influenza and treated with curcumin showed inhibition of influenza-induced expression of TLR2, TLR4, and TLR7, as well as inhibition of activation of MyD88- and TRIF-dependent signaling pathways." (PMID 34282358, 2021). "Taken together, these studies show both MyD88- and TRIF-dependent pathways contribute to influenza-induced disease." (PMID 34282358, 2021). "Fufang-Yinhua-Jiedu Granules (FFYH) was used to treat influenza, and the antiviral effect may be attributed to the suppression of inflammatory cytokine expression by regulating the TLR7/MyD88/NF-κB signaling pathway." (PMID 35123452, 2022). "In WT mice infected with FM1 influenza strain, FTA may play an anti-influenza effect by downregulating key factors such as TLR7, Myd88 and NF-κB in the TLR7 signaling pathway." (PMID 35733131, 2022). "In mice, the rASP-1-adjuvanted seasonal trivalent influenza vaccine (IIV3) induced protection from a lethal H1N1 infection that was dependent on CD4+ T cells, but independent of the production of neutralizing antibodies and MyD88 signaling." (PMID 36119026, 2022). "Eritoran treatment after lethal influenza challenge of wildtype mice, which inhibits both MyD88- and TRIF-dependent signaling, did not block the ability to mount an adaptive immune response to a secondary lethal influenza challenge." (PMID 34282358, 2021). "Upregulation in influenza-infected chicken tissues has not been explored, but MyD88 is upregulated by LPS treatment." (PMID 32477965, 2020). "While in some immune cells TLR7 is the major PRR mediating IFN induction by influenza virus, we found that the absence of TLR7 or its downstream adaptor MyD88 had no impact on the induction of IFNs in influenza-infected epithelia." (PMID 24278020, 2013). "Our data indicate that the inhibitory effect of ST2 on MyD88 dependent TLR signaling does not influence viral clearance during primary influenza infection." (PMID 23483993, 2013). "An increased lung viral load was seen only when MyD88 and IPS-1 (the adaptor molecule for the cytosolic RIG-I pathway) were both absent, suggesting that these pathways can compensate for one another during influenza infection." (PMID 21108806, 2010). "Though not essential for survival, MyD88 does play a distinct role in the adaptive immune response to influenza through regulation of B-cell isotype switching." (PMID 21108806, 2010). "Therefore, we speculate that XJXRY may exert anti-influenza and anti-inflammatory effects by down-regulating key factors (i.e., TLR7, MyD88 and NF-κBp65) of the TLR7 signaling pathway." (PMID 31572491, 2019). "Hence, ST2, as an inhibitor of MyD88 dependent TLR signaling, may influence the host response to S. pneumoniae in mice recovering from influenza in different manners." (PMID 23483993, 2013). "Our previous studies, which showed that protection against influenza infection elicited by the rASP-1-adjuvanted IIV3 vaccine is independent of MyD88, led us to hypothesize that type I IFN, a critical element of anti-viral responses has a significant role for this protection." (PMID 36119026, 2022). "Thus, the TLR4, CD14, MyD88, and NF-κB p65 in TLR4/NF-κB p65 signaling pathway, HIF1 α, VEGF, IL17A, and IL6 in HIF-1α/IL17 signaling pathway may be the targets responsible for the anti-inflammatory function of HSSD in treating influenza." (PMID 36386710, 2022). "In conclusion, our study suggested that TLR4, CD14, MyD88, NF-κB p65, HIF1 α, VEGF, IL17A, and IL6 in the TLR4/NF-κB p65 signaling pathway and HIF-1α/IL17 signaling pathway may be the key targets for the identified active compounds of HSSD to treat influenza by inhibiting inflammatory responses." (PMID 36386710, 2022). "For example, Myd88 is required for the CD8+ T cell response to the arenavirus LCMV, but not for the CD8+ T cell response to influenza." (PMID 19214214, 2009).
influenza (continued). "It was shown that TLR3, TLR7 and MyD88 signaling is not required for efficient T responses during influenza infection, but both TLR7 and MyD88 are critical for B cell responses during influenza infection." (PMID 25539593, 2014). "Since both B cell-intrinsic and -extrinsic TLR signals influenced EFR magnitude and kinetics, we tested whether LPS, a TLR4 agonist that initiates both MyD88 and TRIF signaling, could overcome the lack of EFRs induction after s.c. immunization with influenza virions in alum." (PMID 37407556, 2023).
Stroke (25 papers, 2011 to 2026). Sudden impairment of blood flow to a part of the brain due to occlusion or rupture of an artery to the brain. "However, SCS effectively inhibited the MyD88-p-NF-κb signaling pathway in the ischemic hemisphere, thus improving the pathological microenvironment associated with stroke." (PMID 40365292, 2025). "Tlr4 is frequently implicated in stroke and initiates the downstream Myd88-dependent pathway." (PMID 39062789, 2024). "MyD88 signaling is a hallmark of a response to a thymus independent type 1 (TI-1) antigen, which indicates that a population of IgA + PCs develop following stroke in response to a TI-2 antigen." (PMID 32956832, 2021). "This study investigated whether MyD88-dependent signalling contributes to the damage associated with stroke." (PMID 23483951, 2013). "MANF inhibited inflammatory responses and improved blood-brain barrier integrity after stroke in aged mice via the TLR4/MyD88/NF-κB pathway." (PMID 40919080, 2025). "Our results showed that microbiota depletion triggered very low levels of several inflammatory signaling genes such as Myd88, IL-17ra, Edn1 and Stat3 in the ischemic hemispheres of MiD mice compared to MiS stroke mice." (PMID 40410847, 2025). "The present study aims to investigate short-term add-on efficacy and mechanism of Panax notoginseng (Sanqi) for aspirin resistance in secondary stroke prevention via TLR4/MyD88/NF-κB signaling pathway." (PMID 36550905, 2022). "To determine if the IgA + PC response to stroke is in response to a TI-1 or a TI-2 antigen, we performed stroke surgery on WT and MyD88−/− mice." (PMID 32956832, 2021). "HMGB1 was reported to bind to RAGE or activate the TLR4/MyD88 pathway, both of which promote the reduction of mature monocytes and lymphocytes in the circulation, and lead to subsequent post-stroke immunosuppression." (PMID 31001089, 2019). "In direct contrast, our study demonstrates that Myd88-dependent signalling in hematopoietic cells has a protective effect in stroke." (PMID 23483951, 2013). "The major finding from this study is that hematopoietic cells exhibit a neuroprotective function after stroke that is mediated by MyD88." (PMID 23483951, 2013). "The contribution of MyD88-dependent signalling to the inflammatory progression of infarct following stroke was assessed using the MCAO model of stroke." (PMID 23483951, 2013). "We therefore generated bone marrow chimeras and found that Myd88−/− animals have a smaller stroke infarct than their radiation naive counterparts if their hematopoietic cells are WT." (PMID 23483951, 2013). "The primary objective of this study aims to investigate short-term add-on efficacy and mechanism of Panax notoginseng (Sanqi) for aspirin resistance in secondary stroke prevention via TLR4/MyD88/NF-κB signaling pathway with a more strictly randomized controlled trial (RCT)." (PMID 36550905, 2022). "Using MyD88−/− mice, which lack the ability to undergo TI-1-mediated T-lymphocyte independent B-lymphocyte activation, we observed that there was still a population of IgA + PCs within the infarct of the MyD88−/− mice at 7 weeks following stroke." (PMID 32956832, 2021). "We found that after stroke Myd88−/− animals have a larger infarct volume compared to WT animals." (PMID 23483951, 2013). "We have demonstrated that MyD88-dependent signalling in the hematopoietic cell lineage reduces infarct size following stroke and that infiltrating cells to the site of neuroinflammation are neuroprotective following stroke." (PMID 23483951, 2013). "As an adaptor protein for primarily pro-inflammatory pathways we hypothesized that Myd88-dependent signalling would contribute to brain damage following stroke, and that Myd88−/− mice would exhibit a smaller infarct following MCAO." (PMID 23483951, 2013). "Therefore, we hypothesized that the TLR4/MyD88/NF-κB pathway might be the critical pathway through which Evobrutinib inhibits the pro-inflammatory polarization of microglia following stroke." (PMID 40263985, 2025).
Stroke (continued). "In addition, TEAS can inhibit the TLR4/MyD88/NF-κB pathway, reduce ischemic brain damage after stroke, inhibit inflammation, cell death, and microglia activation, improve the motor neurons in spinal cord downlink control function, and reduce excessive muscle tone." (PMID 39665041, 2024). "Melatonin and the neuropeptide PNX-14 inhibited microglia activation-mediated inflammation after stroke by suppressing the high expression and release of HMGB1 and modulating the subsequent activation of the TLR4/MyD88/NF-κB signaling pathway." (PMID 38740617, 2025). "We then compared the B-lymphocyte response to stroke in WT, MHCII−/−, CD4−/−, and MyD88−/− mice to determine if B-lymphocytes mature into IgA + PCs through a T-lymphocyte and MyD88 dependent mechanism." (PMID 32956832, 2021). "Our data from a combination of IHC and flow cytometry indicate that following stroke, a population of IgA + PCs develops independently of CD4 + helper T-lymphocytes and MyD88 signaling." (PMID 32956832, 2021). "MyD88, a downstream effector molecule of TLR signaling has been shown to be involved in HMGB1-mediated post-ischemic inflammatory response and enhances stroke lesions when compared to MyD88 knockout mice in fMCAO model." (PMID 31291966, 2019). "By blocking the TLR4 receptor, the extent of brain tissue edema, infarct size, and increased neurological damage scores after stroke are reduced in vivo, which possibly occurs via the TLR4/MyD88 signal pathway." (PMID 31001089, 2019). "In terms of key signaling pathways, based on analysis of the tectoridin-stroke PPI network, GO and the KEGG pathway enrichment analysis suggested that PI3K/Akt, Nrf2/HO-1, and TLR4/MyD88/NF-κB play an important role in the therapeutic actions of tectoridin for the treatment of stroke." (PMID 40003867, 2025). "We discovered that the delayed infiltration of B-lymphocytes and IgA + PCs into the infarct following stroke can occur independently of CD4 T-lymphocyte help, and that IgA + PC maturation following stroke does not require MyD88 signaling." (PMID 32956832, 2021). "MyD88 immunoreactivity was significantly higher in the ipsilateral striatal area of control stroke group compared to sham-operated controls (data not shown, p = 0.029), in contrast to miR-669c-3p overexpressing stroke animals (data not shown, p = 0.7057)." (PMID 32560730, 2020). "Here, we show that the increased expression levels of TLR2, TLR4 and TLR8, adaptor protein MyD88, signalling protein TRAF6, TLR downstream signalling proteins such as NF-κB and MAPKs were significantly prevented in IVIg-treated animals compared to control animals following stroke." (PMID 25886362, 2015).
fungal infections (24 papers, 2011 to 2025). "MyD88−/− mice are highly susceptible to fungal infections caused by C. albicans, A. fumigatus, Coccidioides immitis, and Paracoccidioides brasiliensis, as well as C. neoformans, compared to WT mice." (PMID 29518906, 2018). "Impaired MyD88 signaling increases susceptibility to fungal infections such as candidiasis, cryptococcosis, aspergillosis, paracoccidioidosis, pneumocystis and coccidioidomycosis." (PMID 26367276, 2015). "The missense variant in MYD88 is the likely cause of persistent fungal infections that ultimately may have led to the development of early-onset gastric cancer in this patient." (PMID 26700889, 2016). "Indeed, mice deficient in IFNAR have an increased susceptibility to and severity of viral, bacterial, and fungal infections compared to normal mice, and this susceptibility is further enhanced in Myd88-IFNAR double-KO mice." (PMID 22216024, 2011). "One patient with early-onset gastric cancer had a homozygous MYD88 (p.Arg238Cys) TIR domain mutation, recurrent fungal infections, and partial immune defects." (PMID 41479884, 2025). "infection significantly increased PD-L1 expression in OSCC cells through the TLR2/MyD88 and NF-κB pathways, linking fungal infection to chronic-inflammation-driven immune suppression." (PMID 40278081, 2025). "MyD88 knockout mice are prone to multiple fungal infections, demonstrating the vital role of MyD88 in initial responses." (PMID 38143753, 2023). "Malassezia induces IL-17-dependent inflammation and mediated fungal infection via keratinocyte IL-36 receptor/MyD88 signaling in mouse skin." (PMID 36405009, 2022). "This anti-inflammatory function of IL-38 is deeply rooted in the suppression of NF-κB and mitogen-activated protein kinases (MAPKs) signaling by MyD88, which is normally found in some fungal infections (Candidiasis), psoriasis, and rheumatic diseases." (PMID 34830435, 2021). "Under the condition of fungal infection, overexpression of MyD88 was functionally enough for the induction of fungicidal peptide Drosomycin in vitro." (PMID 31333658, 2019). "In contrast, MyD88 mutant flies succumb rapidly after fungal infection and this is correlated to fungal burden." (PMID 27767081, 2016). "MyD88−/− mice have been shown to be sensitive to fungal infections, including C. albicans and A. fumigatus, and MyD88 is required for optimal Th1 responses to fungi in mice." (PMID 25420452, 2015). "Host protection from fungal infection is thought to ensue in part from the activity of Syk-coupled C-type lectin receptors and MyD88-coupled toll-like receptors in myeloid cells, including neutrophils, macrophages and dendritic cells (DCs)." (PMID 25033445, 2014). "The patients with MyD88 deficiency did not have serious and uncontrollable viral and fungal infections, and the bacterial infections in adulthood were also controllable, possibly because of immunological redundancies and an intact adaptive immune response." (PMID 41007776, 2025). "The significant role of MyD88 in fungal infections has been predominantly shown in mouse models." (PMID 29518906, 2018). "Recent studies in individuals who lacked functional MyD88 demonstrated that patients were more susceptible to bacterial infections, as compared to fungal infections." (PMID 29518906, 2018). "In addition to the extrinsic role of MyD88 signaling in immunity to fungal infections, T cell- intrinsic expression of MyD88 is required for resistance to infections with Toxoplasma gondii, LCMV and B. dermatitidis." (PMID 27542117, 2016). "In humans, complete lack of TLR functionality, through mutation of key downstream signalling adaptors such as MyD88 does not predispose individuals to fungal infections." (PMID 25420452, 2015). "While impaired MyD88 signaling reliably enhances susceptibility to numerous fungal infections, the absence of individual TLRs shows varying results, perhaps due to impaired IL-1R family signaling in MyD88-/- mice or due to compensation by other TLRs." (PMID 26367276, 2015).